RUNX3 (RUNX family transcription factor 3)
Diseases named in the same sentence as RUNX3 in open-access papers (continued):
Sharing a sentence is not in itself a finding about the gene and the disease.
tumor (continued). "There were significant correlations between RUNX3 expression and tumor size (P=0.0086), clinical staging (P=0.0079), lymphatic metastasis (P=0.0063) and tumor recurrence (P=0.0056)." (PMID 28828318, 2017). "In this study, based on our previous research data, we first determine the inverse relationship between miR-19 (miR-19a and miR-19b) and RUNX3 which is also identified the reduced expression in tumour tissues by real-time PCR and IHC." (PMID 29340016, 2017). "In the present study, RUNX3 expression was decreased in HCC tumor tissues compared with normal hepatocellular tissues." (PMID 28977878, 2017). "Firstly, we analysize the relationship on expression of miR19 and RUNX3 with different tumour grades according to WHO classification scheme." (PMID 29340016, 2017). "We employed univariate and multivariate Cox regression analyses with RUNX3 expression, tumor volume, age, pT status, pN status and TNM stage." (PMID 29254144, 2017). "The expression of miR-30a is increased by overexpression of a putative tumor suppressor, Runt-related transcription factor 3 (RUNX3)." (PMID 27992370, 2017). "When the clinicopathological features were compared according to SMAD4 and RUNX3 expression status, we found SMAD4 loss was associated with increased tumor size (p = 0.030), higher pN stage (AJCC 8th ed)." (PMID 29100342, 2017). "RUNX3 acts as a tumor suppressor in many cancers, including stomach, bladder, breast, lung, brain, colorectal, pancreatic, and hepatocellular carcinoma." (PMID 28030842, 2017). "RUNX3, a member of this family, is known as a tumor suppressor in many types of cancers, although such a paradigm was challenged by some researchers." (PMID 29201108, 2017). "Despite this discrepancy, it has been appeared that exogenous expression of the RUNX3 in tumor cells induces apoptosis and cell cycle arrest, reduces tumor bulk and vascularity, inhibits metastasis, and increases sensitivity of tumor cells to the chemotherapy." (PMID 29201108, 2017). "Significant differences were found in RUNX3 expression levels between tumor and peritumoral infiltrate (p-value < 0.0001) and between the adjacent mucosa and the peritumoral infiltrate (p-value < 0.0001) samples." (PMID 27566570, 2016). "Specifically, ARID1A levels were reduced in 12.5% of the tumor tissues, whereas RUNX3 levels were lower in 87.5% of the tumor tissues analyzed." (PMID 27566570, 2016). "An altered methylation pattern of APC, CDH13, MGMT, MLH1 and RUNX3 genes is a well recognized characteristic of CRC tumor cells." (PMID 26862732, 2016). "We also studied RUNX3 expression by immunohistochemistry (IHC) in 40 samples, and validated differences in methylation levels between tumor, normal, and immune tissue in 14 additional samples." (PMID 27566570, 2016). "Studies also showed that hypermethylation and subsequent silencing of RUNX3 are prevalent in solid tumors of the breast and stomach, suggesting a tumor suppressing role of RUNX3." (PMID 27007162, 2016). "We assessed a methylation panel of 5 genes to study their association to GC progression and microsatellite instability (MSI), and studied the role of RUNX3 in GC pathogenesis and the tumor immune microenvironment." (PMID 27566570, 2016). "In this study, we showed that baicalein increased FOXO3a, a transcription factor with known anti-tumor activity and RUNX3, another tumor suppressor, protein expression in a dose-dependent fashion in A549 and H1650 cells." (PMID 25948105, 2015). "While the jury is still out, RUNX3 P1 methylation has links with key mediators of anti-tumor responses that warrant exploration of its use in similar context." (PMID 26682246, 2015).
tumor (continued). "The gastric epithelium of Runx3 knockout mice exhibits hyperplasia, a reduced rate of apoptosis, and reduced sensitivity to TGF-β, suggesting that RUNX3 tumor suppressor operates downstream of the TGF-β signaling pathway." (PMID 26375442, 2015). "RUNX3, a member of the family of transcription factors that contain the runt domain, is located at human chromosome 1p36 and was identified as a tumor-suppressor in breast, bladder and lung cancer." (PMID 26134263, 2015). "Most tumor studies show a low probability of RUNX3 DNA methylation in normal tissue specimens, so the observation that RUNX3 in newborn rat lung tissues displayed differential DNA methylation at different intervals after birth is puzzling." (PMID 26104385, 2015). "RUNX3 is a gene which is highly expressed in LCLs and has been shown, paradoxically, to act both in promoting and suppressing tumor growth." (PMID 26422229, 2015). "Nevertheless, we caution against over interpretation of these observations, as RUNX3 P1 hypomethylation also marks other immune lineages that can elicit both pro- and anti-tumor effects." (PMID 26682246, 2015). "RUNX3 (runt-related transcription factor-3) has been reported to suppress tumor tumorigenesis and metastasis in different human cancers." (PMID 24475196, 2014). "In view of the dual role of Runx3, which inhibits the proliferation of tumor cells and regulates T and B cells, it is considered to be an important target for antitumor immunity." (PMID 24748977, 2014). "Our results showed that there was a significantly lower level of RUNX3 expression in the tumors than in the tumor adjacent normal prostate tissues (P<0.01)." (PMID 24475196, 2014). "As a widely accepted tumor suppressor gene, RUNX3 (human runt-related transcription factor 3) functions in major physiological and pathological processes." (PMID 25551195, 2014). "Collectively, our data suggest a novel molecular mechanism for the tumour suppressor activity of RUNX3." (PMID 24447545, 2014). "Given the prominent role of VEGF in tumor angiogenesis, we detected the effect of RUNX3 overexpression on VEGF activity." (PMID 24475196, 2014). "The results suggested that the altered tumor growth and metastasis by restored RUNX3 expression was correlated with altered angiogenesis." (PMID 24475196, 2014). "RUNX3 has been recently reviewed as a tumor suppressor, specifically in human BRCA, with decreasing expression associated to disease progression." (PMID 25033876, 2014). "Our in vitro and vivo results demonstrated that RUNX3 inhibited tumor growth by suppressing tumor angiogenesis." (PMID 24475196, 2014). "Runt-related transcription factor 3 (RUNX3) is a putative tumour suppressor via regulating the expression of a series of target genes." (PMID 24447545, 2014). "The prevalence of lymph node involvement, tumor size (T1–T2 vs T3–T4) and histological grade was significantly greater in RUNX3-negative cases (RUNX3 unmethylated groups) than in RUNX3-positive cases (OR = 0.25, CI = 0.14–0.43, P<0.00001)." (PMID 25229459, 2014). "Because RUNX3 expression decreased tumor cell migration and invasion in vitro, a tail vein metastatic assay was used to analyze the in vivo effects of RUNX3 expression on the metastatic potency of DU145 cells." (PMID 24475196, 2014). "We injected BGC-823 cells transfected with pcDNA3.1 or RUNX3/pc3.1 into the tail vein of nude mice and examined their lungs for tumour seeding." (PMID 24447545, 2014). "To investigate the effect of RUNX3 treatment on tumor growth in vivo, we established a subcutaneous tumor in nude mice." (PMID 24475196, 2014). "The prevalence of lymph node involvement, tumor size (T1–T2 vs T3–T4) and histological grade was significantly greater in RUNX3-negative cases (RUNX3 unmethylated groups) than in RUNX3-positive cases, with OR = 0.25, CI = 0.14–0.43, P<0.00001." (PMID 25229459, 2014).
tumor (continued). "Ches1, Tcf3, Ccnc and Gfi1 are transcriptional repressors, Pten and Runx3 are tumor suppressors, and Cdkn1b is a cell cycle inhibitor." (PMID 24859236, 2014). "Up-regulation of miR-130a directly inhibited expression of tumor-suppressor gene RUNX3 leading to activation of Wnt/β-catenin signaling and sequent drug resistance." (PMID 24788655, 2014). "RUNX3 and other signal transducers such as Smad are collectively required for the tumor suppressor activity of the TGF-β pathway." (PMID 23457532, 2013). "Collectively, these observations suggest that Runx3 serves as an important tumor suppressor against Ras-induced tumorigenicity by safeguarding against Hmga2-mediated plasticity and stemness." (PMID 23950932, 2013). "Given the potential role of RUNX3 in TGF-β signaling, it is possible that the tumor suppressor activity of RUNX3 is realized by regulating cell migration and invasion." (PMID 23457532, 2013). "Our results demonstrated that RUNX3 expression was decreased in RCC tissues compared with tumor adjacent normal renal tissues." (PMID 23457532, 2013). "Some examples of tumor suppressors or oncogenes with dual functions exit, including Myc, Runx3, Notch, p21 just to mention a few." (PMID 24040083, 2013). "There has been evidence that RUNX3 can function as a tumor suppressor by regulating cancer growth and angiogenesis." (PMID 23457532, 2013). "Among the three RUNX family members, RUNX3, in particular, has been shown to play a tumor suppressor role in several cancers and its expression levels are down-regulated in cancer tissues." (PMID 23457532, 2013). "In another study, overexpression of Src resulted in the mislocalization of RUNX3, a transcription factor that has tumor suppressor function." (PMID 23585863, 2013). "Intriguingly, RUNX3 is located on human chromosome 1p36, a region which has long been suggested to be a tumor suppressor locus in a variety of human cancers." (PMID 24078903, 2013). "The RUNX3 expression was significantly correlated with tumor size (P<0.001), depth of invasion (P<0.001), and of TNM stage (P<0.001)." (PMID 23457532, 2013). "Our data showed that decreased expression of RUNX3 showed a significant correlation with tumor size (P<0.001)." (PMID 23457532, 2013). "Runx3 is a novel tumor suppressor in gastric carcinogenesis and an important factor for differentiation of chief cells in the normal gastric fundic mucosa." (PMID 23243425, 2012). "The TGFβ superfamily transcription factor, runt-related transcription factor 3 (RUNX3), functions as a tumor suppressor gene and is involved in mediating apoptotic processes." (PMID 22645611, 2012). "Because migratory potential is a common feature in the process of tumor metastasis, we then studied the influence of RUNX3 on the migratory abilities of CCRCC cells in vitro by Transwell assay." (PMID 22457727, 2012). "Restored RUNX3 expression in 786-O cells clearly inhibited the growth of 786-O-RUNX3 cells in vitro (P < 0.05), showing that RUNX3 has a tumor-suppressive function in human CCRCC cells." (PMID 22457727, 2012). "As a strong candidate for a tumor suppressor, Runx3, a member of runt-related transcription factors (Runx1, Runx2, and Runx3), has been widely studied in a variety of human cancers." (PMID 23243425, 2012). "RUNX3 is a known regulator of major developmental pathways, and has recently been reported as a candidate tumor suppressor." (PMID 21867527, 2011). "Among them, Runx3 is a tumor suppressor that has antiproliferative effect and induces TGF-β-dependent apoptosis." (PMID 24250365, 2011). "Runx3, a member of Runt-related transcription factor (Runx) proteins with tumor suppressor effect, is a tissue–restricted and cancer related transcription factor that regulate cell proliferation and growth, as well as differentiation." (PMID 24250365, 2011). "RUNX3 protein expression in human HCC tissue was compared to that in the corresponding tumor-free resection margins using immunohistochemical analysis." (PMID 21205319, 2011).
tumor (continued). "Although some studies have reported significant differences in methylation status and protein expression of RUNX3 in relation to tumor invasion depth, the overall results of the current study failed to support the existence of such a relationship." (PMID 21867527, 2011). "In this study, we used tissue microarrays containing a very large number of primary CRC samples to investigate the expression of RUNX3 in relation to tumour features and to patient outcome." (PMID 19223906, 2009). "With advancing tumour stage, expression of RUNX3 in the nucleus decreased, whereas expression restricted to the cytoplasmic compartment increased." (PMID 19223906, 2009). "The high specificity of RUNX3 methylation in tumour tissue relative to normal colonic mucosa has led to its inclusion in a panel of five genes proposed for the standardised classification of the CpG island methylator phenotype (CIMP) in CRC." (PMID 19223906, 2009). "Nuclear RUNX3 expression was associated with significantly better patient survival compared to tumours in which the expression of RUNX3 was restricted to the cytoplasm (P=0.025)." (PMID 19223906, 2009). "In cases with metastatic lesions, more aggressive tumour cells from the original lesion exist, such as RUNX3-methylated cells." (PMID 18475302, 2008). "Tle6-like;TLE6D directly interact with the gastrointestinal tumor suppressor RUNX3 and antagonize RUNX3 target transactivation." (PMID 18551179, 2008). "Both Tle6-like and TLE6D interact with GI tumor suppressor, RUNX3, and antagonize RUNX3 gene target tranactivation." (PMID 18551179, 2008). "A more recently proposed molecular mechanism for the anti-tumor activity of RunX3 is the inhibition of cancer angiogenesis, growth and metastasis." (PMID 19412438, 2007). "The tumor suppressor activity of RunX3 was demonstrated in nude mice when an increase in the level of runX3 expression resulted in decreased tumorigenicity." (PMID 19412438, 2007). "Within the tumour, downregulation of RUNX3 expression ranged from 74.7 to 85.7% in the three groups." (PMID 15685235, 2005). "Downregulation of the RUNX3 expression rate in tumour was 74.7% (65 in 87 cases) in the GCI group, 82.1% (24 in 28 cases) in the RB group, and 85.7% (18 in 21 cases) in the RM group." (PMID 15685235, 2005). "Recent evidences of frequent silencing of hMLH1, p16, RUNX3, and other tumour suppressor and tumour-related genes by promoter hypermethylation suggests that epigenetic alterations play the most important role in gastric carcinogenesis." (PMID 16265349, 2005). "The frequency of promoter hypermethylation of the tumor suppressor gene loci included in the panel was FHIT 28%, FANCF 24%, Cyclin-D2 12%, BRCA2 4%, and RUNX3 56% of the 25 tumours." (PMID 15574200, 2004). "Importantly, engineering CAR-T cells to express CXCR6 or RUNX3 enhances their intratumoral persistence and tumor control, highlighting the translational potential of modulating this pathway." (PMID 41479900, 2025). "Furthermore, the tumour-promoting TF Runx3 previously shown to be upregulated in TAMs was downregulated by SFV/Luc and SFV/TNFα." (PMID 40547518, 2025). "Emerging evidence indicates that RUNX3 hypermethylation, frequently observed in various malignancies (e.g., bladder, lung, and colorectal cancers), leads to transcriptional silencing and contributes to tumour initiation and progression." (PMID 40559899, 2025). "It has been suggested that it may disrupt a binding site of the c-MYC transcription factor, affecting the regulation of RUNX3, a transcription factor that also functions as a tumor suppressor." (PMID 40507438, 2025).
tumor (continued). "Additionally, the well-known tumor suppressor gene RUNX3 was significantly up-regulated (+8.93) in curcumin-treated cells, further supporting its potential role in curcumin-mediated tumor suppression." (PMID 40430278, 2025). "CLDN1 acts as a tumor suppressor and is a direct target of RUNX3." (PMID 40687428, 2025). "While AKT inhibition alone induced a CD62L+ central memory–like phenotype with impaired tumor-resident and effector functions in CAR-T cells, AKT inhibition in combination with RUNX3 overexpression improved cytotoxic potential and tumor infiltration in a pancreatic ductal adenocarcinoma model." (PMID 40693464, 2025). "In addition, CagA can repress phosphatase activity and inactivate runt related transcription factor 3(RUNX3) that serves as a tumor inhibitor, leading to tumorigenesis." (PMID 39035354, 2024). "Notably, RUNX1 was upregulated, while RUNX3 was downregulated in COAD tumor tissues, with statistical significance." (PMID 39822248, 2024). "Apart from these functions, RUNX3 is also a significant tumor suppressor gene." (PMID 38956704, 2024). "In RCC, RUNX3 was found to suppress tumor growth, migration, angiogenesis and metastasis." (PMID 38172737, 2024). "The density of CD8+ T lymphocytes infiltrating tumor tissue may be influenced by the transcription factor (TF) Runx3, which is among the factors impacting their aggregation or depletion in HCC." (PMID 38426090, 2024). "We found that BOS cells primarily expressed the longer p46 isoform of RUNX3, which plays a tumor suppressor role and might explain the decreased transformation in BOS compared with AML-ASXL1 that expresses the shorter p44 isoform." (PMID 39614348, 2024). "Furthermore, high RUNX3 methylation levels presented an ill-defined tumor margin and left-sided tumors, two characteristics, respectively, not present in VHL gene mutation." (PMID 38666933, 2024). "In tumor microenvironment, Runx3 was also found as a critical regulator of CD8 + T cell residency." (PMID 38172737, 2024). "RUNX3 acts as a developmental regulator, and it has been generally described as a tumor suppressor." (PMID 38172737, 2024). "Furthermore, in half of GC cases, promoter hypermethylation, as well as hemizygous deletion, lead to RUNX3 tumor-suppressor gene silencing." (PMID 38542354, 2024). "RUNX3 pathway was related with CD8 + T cell dysfunction in tumor microenvironment." (PMID 38172737, 2024). "RUNX3 has been defined as both a tumor suppressor and a tumor promoter, and it can play such contradictory roles even in the same tumor, which may reflect the complex role of RUNX3 in tumorigenesis." (PMID 38430423, 2024). "This indicates that not only does MEX3C interact with RUNX3 in LUAD cells but other factors controlled by RUNX3 could be contributing to tumor progression." (PMID 38424632, 2024). "Usually, RUNX3 acts as a tumor suppressor gene in various human neoplasms." (PMID 38172737, 2024). "Many studies have reported the role of RUNX3 in inhibiting cancer cell migration and tumor growth." (PMID 37719863, 2023). "It is possible that PIN1 might be directly or indirectly involved in the tumor suppressor function of RUNX3, and the regulation could be cell-type- or cancer-type-specific." (PMID 36899853, 2023). "A crucial tumour-suppressive role of RUNX3 is angiogenesis prevention and tumour invasion." (PMID 37759525, 2023). "RUNX3 is another tumor suppressor of which the activity is regulated by JAB1." (PMID 36899853, 2023). "This inactivation might be owed to the fact that the genetic location of RUNX3 clusters with a range of tumor suppressors and hyper-methylation of chromatin is common in this region." (PMID 36831308, 2023). "Moreover, miR-106a overexpression correlates with the downregulation of runt-related transcription factor 3 (RUNX3), a tumor suppressor known to inhibit cell progression and tumorigenesis." (PMID 37627777, 2023).